RET (ret proto-oncogene)
Diseases named in the same sentence as RET in open-access papers (continued):
Sharing a sentence is not in itself a finding about the gene and the disease.
tumor (continued). "Additionally, selpercatinib was evaluated in 42 patients with RET-fused tumors of different histologies other than lung and thyroid; durable antitumor activity across different tumor subtypes was observed, with only minor adverse effects." (PMID 36839989, 2023). "Therefore, to potentially complement sNGS, we validated the Idylla Genefusion assay for ALK, ROS1, and RET rearrangements and MET exon 14 skipping variant detection using 34 tumor samples that were previously orthogonally tested via FISH and NGS." (PMID 37628603, 2023). "Genetic screening performed on a tumour biopsy specimen after Selpercatinib but before Pralsetinib revealed RET M918T, RET V804M, RET G810S mutations, and lastly a CDKN2A LOH in addition to the original RET mutation." (PMID 37835559, 2023). "There might be several other reasons for this observation including differences in RET expression in the primary tumour and metastases, differences in detection of RET expression across the various antibodies employed or simply spurious results." (PMID 39516358, 2023). "Based on the identified prognostic factors, age, gender, tumor diameter, and RET alteration, we constructed the LNM prediction nomogram, validated by the calibration, DCA, and clinical impact curve, all the results indicated that the nomogram presenting a high accuracy." (PMID 37081757, 2023). "This review summarizes the genetic landscape of MTC at both germline and somatic levels to understand the molecular basis and the natural history of the tumour, mainly but not exclusively, linked to RET proto-oncogene genetic abnormalities." (PMID 37835559, 2023). "Additionally, given the heterogeneous genetic landscape of advanced BTCs, many harbor genetic aberrations that are common among solid tumors, including RET fusions, tropomyosin receptor kinase (TRK) fusions, and high tumor mutational burden (TMB)." (PMID 37046766, 2023). "Furthermore, NB cells and tumor samples demonstrated high RET expression levels, and its activation induces invasive spread NB in animal models." (PMID 36839989, 2023). "New perspectives include next-generation RET inhibitors able to overcome resistance mechanisms responsible for disease progression to standard mTKIs and RET inhibitors, and immunotherapy for MTC presenting with high tumor mutational burden." (PMID 37979019, 2023). "We chose age, tumor diameter, RET fusion, and gender to construct the LNM predicting nomogram." (PMID 37081757, 2023). "Since it is unclear how knowledge of a specific somatic (acquired) RET mutation should impact initial clinical management and follow-up, it is not routinely necessary to evaluate primary tumor samples for RET mutational status." (PMID 37979019, 2023). "Notably, the use of Selpercatinib in patients with RET fusion-positive NSCLC who have undergone platinum-based chemotherapy or remained untreated resulted in a significant reduction in tumor growth with minimal toxicity." (PMID 37375228, 2023). "Therefore, further investigation is required into more data on history of recurrence, radiation history, gene aberration, tumor focality among other aspects to enhance our understanding of RET::PTC rearrangements." (PMID 37188126, 2023). "Therefore, more detailed research support is needed to understand better the effect of clinical features on improving the prognosis of tumor patients with RET-TKIs." (PMID 37603207, 2023). "While one cell line model has indicated a role for RET expression alone in the endocrine-resistant phenotype, the bulk of the findings above indicate that primary tumor expression of the GFL family ligands is the critical factor governing RET-mediated therapeutic resistance." (PMID 36918928, 2023).
tumor (continued). "We found that after adjusting the potential impact factors, patient age (p = 0.002), tumor diameter (p = 0.034), and RET fusion (p = 0.032) still as the prognostic factor to the presence of positive lymph node, while patient gender also showed a marginal prognostic value (p = 0.08)." (PMID 37081757, 2023). "Moreover, RET is activated and can promote motility and colony formation in metastatic OS cells, contributing to the higher resistance of this tumor type to different chemotherapeutic agents." (PMID 36839989, 2023). "The second most common tumor type with frequent RET fusions was papillary thyroid cancer (22.8%)." (PMID 37360768, 2023). "This paved the way for the first tumor-agnostic selective RET inhibitor US FDA approval in 2022." (PMID 37627175, 2023). "RET and a subset of nine genes was found to be overexpressed in more than 4% of tumor samples." (PMID 38132167, 2023). "Another study showed that RET amplifications only affect tumours carrying mutations, not playing a role in tumourigenesis but potentiating the transforming activity of the RET oncogene." (PMID 37835559, 2023). "Despite this prior therapy-mediated serial genetic evolution of RET, the plasma frequency of both the enrolling and secondary RET mutations decreased with selpercatinib treatment in all patients, indicating that the tumor cell with both RET alterations remained sensitive to RET inhibition." (PMID 35304457, 2022). "Multiple TKIs that target RET have shown minimal therapeutic benefit in patients with RET rearrangements in their malignancies, includes cabozatinib (tumor response rate of 28% and median PFS of 5.5 months) and vendatinib (response rate of 18% and median PFS of 4.5 months)." (PMID 36291069, 2022). "In our case pralsetinib exhibited a significant response in a patient with NSCLC and an RET fusion and transformed the unresectable tumor into a resectable tumor; however, 26% of the tumor cells were still alive after pralsetinib neoadjuvant treatment, indicating the necessity of complete resection." (PMID 35223529, 2022). "RET activation promotes cancer progression in several tumor types." (PMID 35044452, 2022). "Indeed, patient-derived CRC tumor cells harboring NCOA4-RET fusion were sensitive to the treatment with vandetanib, a multi-kinase inhibitor with non-selective RET activity." (PMID 35957881, 2022). "Hence, we performed both gene- and pathway-level enrichment analyses using targeted NGS results of tumor tissues collected from 380 baseline RET+ patients." (PMID 36059009, 2022). "RAS-mutant, BRAF, and RET/NTRK fusions were mutually exclusive events in every tumor analyzed." (PMID 35015563, 2022). "PHLPP1 is related to the RET signalling pathway and known for the promotion of tumor progression." (PMID 36037157, 2022). "While the opposing paradigms of RET function may present challenges in the treatment of RET-altered CRC tumors, further analyses are required to determine whether tumor-suppressive or oncogenic RET occurs in specific subpopulations of CRC tumors." (PMID 35957881, 2022). "In 1–2% of NSCLC patients, RET gene rearrangements can enhance tumor development." (PMID 36291069, 2022). "In non-tumor tissues, RET signaling is critical for normal embryonic kidney development." (PMID 35957881, 2022). "In case of advanced unresectable or metastatic MTC with germline RET testing not available or negative, a molecular screening should be performed on tumor tissue to search for somatic RET mutations." (PMID 35600349, 2022). "Subsequent identification of ALK rearrangements and several cancer‐driver events, including ROS1, NRG1, NTRK1/RET fusion, BRAF (V600E) mutation, or MET amplification/Exon14 skipping, strengthened the concept of oncogene addiction and tumor heterogeneity as a pillar of modern cancer therapeutics." (PMID 35838331, 2022). "Other compounds such as SL-1001 showed promising activity against RET-driven tumor models." (PMID 35422765, 2022).
tumor (continued). "MTC rarely shows a tumor capsule, which seems to correlate with a better prognosis and absence of nodal metastases, regardless of RET or RAS mutational status." (PMID 35574005, 2022). "In addition to its antiangiogenic activity, anlotinib suppresses tumor cell growth and migration by blocking c-Kit, c-Met and RET." (PMID 34724131, 2022). "In addition, cabozantinib was predicted to exert a direct tumour proapoptotic induction through inhibition of several receptors, including RET." (PMID 35106125, 2022). "Therefore, a second-generation of highly selective RET inhibitors were developed both to maintain the anti-tumor efficacy and to improve the safety profile." (PMID 35422765, 2022). "RET signaling can be involved in the evasion of growth suppression, resistance to the cell death, progress of the replicative immortality, induction of the angiogenesis and activation of the tumor invasion and metastasization." (PMID 35422765, 2022). "RET/PTC3 was associated with the highest number of aggressive features while BRAFV600E and RET/PTC1 conferred milder tumor phenotype, and tumors with ETV6ex4/NTRK3 or an unknown oncogene were the least aggressive." (PMID 34282777, 2021). "Predictive biomarkers include gene fusions in ALK, ROS1, NTRK, and RET, sensitizing EGFR gene mutations, BRAF V600E point mutations, MET exon 14 skipping mutations and amplifications, PD-L1 expression, ERBB2 mutations, and tumor mutational burden." (PMID 33771190, 2021). "Recently, the tumor suppressor functions of RET have been taken into consideration." (PMID 33906292, 2021). "In summary, our findings suggest that the role of ALK and RET in NB tumor formation is complex; however, dual inhibition of these two RTKs may be beneficial in ALK-driven NB." (PMID 33921066, 2021). "Furthermore, the correlation of RET with clinicopathological features including age, gender, location of the tumor, grade, and stage was evaluated." (PMID 33906292, 2021). "Clinicopathologically, RET/PTC3 was associated with solid growth pattern and higher tumor aggressiveness, BRAFV600E and RET/PTC1 with classic papillary morphology and mild clinical phenotype, and ETV6ex4/NTRK3 with follicular-patterned PTC and reduced aggressiveness." (PMID 34282777, 2021). "Anlotinibalso suppresses tumor growth by blocking c-Kit, RET, Aurora-B, c-FMS, and DDR1." (PMID 34421608, 2021). "While the preceding studies established the tumor-suppressing role of GIPC2 in sporadic PPGLs, we further explored whether GIPC2 had a role in RET mutation-related hereditary PPGL, since all 7 RET-mutated cases in our cohort had GIPC2 loss." (PMID 33947839, 2021). "Thus, to address the importance of RET and TRKA inhibition for the anti-tumour effects, we took advantage of solvent front RET (G810R) or TRKA (G595R) mutants that display resistance to Pz-1." (PMID 34373541, 2021). "Regarding alectinib, its inhibition of RET might occur through modulation of the tumour immune response." (PMID 33659043, 2021). "One tumor displayed a fusion whose 5′-end contained a portion of TBL1XR1 (transducin (beta)-like 1 X-linked receptor 1; located on chromosome 3q26.32), and the 3′-end—a portion of RET (located on chromosome 10q11.2)." (PMID 34282777, 2021). "On the other side, alectinib-induced RET inhibition might contribute to reducing the tumour immune evasion mechanisms." (PMID 33659043, 2021). "Clinicopathologically, RET/PTC3 was associated with solid growth pattern and higher tumor aggressiveness, BRAFV600E and RET/PTC1 with classic papillary morphology and mild clinical phenotype, and ETV6ex4/NTRK3 with follicular-patterned PTC and the reduced aggressiveness." (PMID 34282777, 2021). "However, the relationship between the RET fusion gene and brain metastasis can be referenced by the mechanism of RET gene and tumor metastasis." (PMID 31769228, 2020).
tumor (continued). "Regarding sporadic tumors, RET somatic mutations are not present in each tumor, whereas the correlation between the type of mutation and clinical features is not so clear." (PMID 33112827, 2020). "Activation of the RET proto-oncogene might constitute one of the molecular drivers of gastric inflammatory and neoplastic diseases." (PMID 32708070, 2020). "While the non-tumor HBECp cell line displayed only marginal sensitivity to these compounds, growth of RET-driven cell lines was reduced at low nanomolar concentrations of the RET inhibitors." (PMID 33318047, 2020). "Our data suggest that RET could be up-regulated in tumour macrophages, thereby limiting inflammation and enhancing MMP2 production within the tumour microenvironment." (PMID 33020210, 2020). "For instance, miR-153-3p has been shown to be a RET-regulated tumor suppressor miRNA in MTC." (PMID 32637757, 2020). "Similar to the RET Y1090* truncating mutation from the M5 tumor, a truncating mutation in another tyrosine kinase, TEC Y233*, was present in this tumor as a variant of unknown significance." (PMID 31963394, 2020). "Other second-line treatments may be proposed upon tumor progression for cases with genomic alterations in RET, MET, NTRK, HER2, or other genes, but the patient is also included into a clinical trial most of the time, at least in France." (PMID 32294880, 2020). "The detection of an expressed CCDC6-RET gene fusion in a tumor metastasis by RNA-based NGS suggested that RET inhibition might be an effective treatment option." (PMID 32292131, 2020). "Patients without somatic RET mutation demonstrated significantly longer survival than those harboring RET mutation in tumor cells." (PMID 33112827, 2020). "Clinical information for analysis included DE-mRNA signature, age, PFI status, mutational status of BRAF V600E, RAS, RET, NTRK1, and TERT, sex, histological subtype, T stage, N stage, M stage, AJCC stage, residual tumor status, extrathyroidal extension, multifocality, and anatomic site." (PMID 33553144, 2020). "The recommendations that we have produced for NSCLC, including for RET fusion detection, may be extrapolated to other tumor type or tumor agnostic settings as the field of precision oncology continues to grow." (PMID 33553195, 2020). "Being a multitarget kinase inhibitor, sorafenib blocks tyrosine kinase signalling receptors (VEGFR, PDGFR, and RET) and inhibits downstream Raf serine/threonine kinase activity to prevent tumor growth by antiangiogenic, antiproliferative, or proapoptotic effects that promote tumor cell apoptosis." (PMID 32566073, 2020). "The optimal diagnostic strategy to identify tumors harboring RET gene fusions, RET point mutations, or other actionable driver mutations in malignancies, including ATC, is, therefore, a broad-based NGS approach combining analysis of both tumor DNA and RNA." (PMID 32292131, 2020). "MTC samples harboring the RET C634 mutation presented a higher expression of VEGRF3 and KIT compared with the RET M918T-mutated and non-RET mutated tumor samples." (PMID 33112827, 2020). "Furthermore, it would be interesting to study its dual role in face and retina embryology, and to extend targeted investigations of RET hotspots in these developmental abnormalities to facilitate counselling, follow-up, and tumor prevention." (PMID 32948239, 2020). "Similarly, an ALK fusion was noted in the CTCs, matching the patient’s primary tumor (P 17), and a 3′ deletion of RET was found in recovered CTCs from a patient with a RET rearranged tumor (P 26)." (PMID 31947893, 2020).
tumor (continued). "Similarly, pralsetinib demonstrated durable, potent, and broad anti-tumor activity in NSCLC patients with advanced RET-fusions (Clinicaltrials.gov identifier: NCT03037385)." (PMID 33182254, 2020). "The following tumor mutations were reported in patients with clinical benefit: cKIT (n = 1), CSF-1R (n = 1), PDGFRα (n = 2), PDGFRβ (n = 1), VEGFR1 (n = 1), VEGFR2 (n = 2), FLT3 (n = 1), FGFR2 (n = 2), RET (n = 1), and TrkA (n = 1)." (PMID 32292573, 2020). "Genomic analysis found that her tumor did not contain any common RET mutations but did harbor a BRAF V600E mutation." (PMID 32231814, 2020). "The tumour harboured BRAF V600E mutation and a novel germline point mutation in the RET gene, with unknown clinical and pathological meaning." (PMID 31921336, 2019). "We tested whether expression of Irk2DN (an inwardly-rectifying potassium channel required for cyteneme-mediated signaling), diaRNAi, or SCARRNAi in the RET-mutant cells affects tumor growth and survival." (PMID 31568500, 2019). "RET/PTC-positive samples were associated (not statistically significant) with a higher rate of tumor growth (mostly T3/T4 classification), more frequent extrathyroidal extension, intravascular invasion and multifocality compared to BRAF-positive samples." (PMID 31085772, 2019). "Moreover, RET-induced cell migration requires integrins, and β3 integrin (Itgb3) expression correlates with RET-mediated invasion in a tumor xenograft model." (PMID 31015297, 2019). "RET depletion in control and lamin B1 KD cells resulted in a significant decrease in tumor volume." (PMID 31015297, 2019). "Nevertheless, inhibition of RET may be an effective treatment option in RET-altered BC patients and, most importantly, a combined treatment may delay drug resistance, dissemination of tumor cells and metastasis." (PMID 35582269, 2019). "No other significant difference was found analyzing for the presence or absence of distant metastases, RET mutations, calcitonin value, and tumor size." (PMID 30911297, 2019). "RET is a well characterized contributor to the neoplastic process, acting as an oncogenic driver in several cancers, and has been more recently recognized as a critical determinant of invasion and spread in diverse tumor types." (PMID 30666215, 2018). "In the second pattern, the primary tumor was RET negative, and different metastases of the same patient were either positive or negative for a specific RET mutation." (PMID 29515777, 2018). "RET mRNA levels in patient ID0110M’s MTC were significantly higher than those found in seven other MTCs with various amino-acid substitutions at position 634 in RET, including two with the missense p.Cys634Arg mutation present in patient ID0110M’s tumor." (PMID 30321177, 2018). "In particular, “off targets” effects of TKIs could be considered a better therapeutic option in thyroid or lung tumours that carry CCDC6/RET fusion protein, in order to avoid tumour progression and TKIs resistance." (PMID 29455670, 2018). "Now it is needed to investigate in detail the mechanisms of resistance related to the specific molecular alterations carried by the tumour and, thus, in our case, the drivers of and/or the mechanisms underlying the “de novo” and acquired resistance for ALK, ROS and RET fusion kinases." (PMID 29455670, 2018). "However, GFL-mediated activation of wildtype RET is an increasingly recognized mechanism promoting tumor growth and dissemination of a much broader group of cancers." (PMID 30666215, 2018). "In addition, somatic mutations in the previously known genes VHL, RET, MAX, and HRAS were found in one tumor each, in agreement with frequencies in previous reports." (PMID 29159601, 2018). "Taken together, these data suggest that targeting GFRA1 could have an impact on different tumor subsets, with unique toxicity and activity profiles compared with RET." (PMID 29796165, 2018).